ETS1 (ETS proto-oncogene 1, transcription factor)
Diseases named in the same sentence as ETS1 in open-access papers (continued):
Sharing a sentence is not in itself a finding about the gene and the disease.
lung carcinoma (continued). "The present study identified six hub genes that were related to lung cancer, including mTOR, NF1, CHD7, ETS1, IL-6, and COL1A1, which might be a potential target for lung cancer." (PMID 36211008, 2022). "In conclusion, the present study screened 46 DEMs in GSE17681 and 1029 DEGs in GSE18842 and identified six hub genes related to lung cancer, including mTOR, NF1, CHD7, ETS1, IL-6, and COL1A1, which might be potential targets for lung cancer." (PMID 36211008, 2022). "Transcriptomic data from METex14Del-expressing cells, stimulated or not by HGF, were mapped onto this lung cancer reference network and revealed activation of a major regulatory node composed mainly by the highly influential transcription factors ETS1, FOSL1 and SMAD3." (PMID 41184222, 2025). "In addition, an RNA Ap specific to Ets1, an oncogenic transcription factor, conjugated to PLGA particles, was shown to increase gefitinib’s anticancer effects specifically in Ets1-overexpressing, gefitinib-resistant H1975 lung cancer cells." (PMID 35159698, 2022). "Also, in lung cancer, Ets-1 protein levels correlated with tumour size, lymph node status and tumour stage." (PMID 15365563, 2004). "Downregulation of the ETS1 gene can inhibit cell proliferation and migration in non-small cell lung cancer (NSCLC) cells, slowing the progression of lung cancer." (PMID 40181983, 2025).
colon carcinoma (24 papers, 2004 to 2025). "Furthermore, it was demonstrated that the p42 splice variant of ETS1 can cause human colon cancer cells to undergo apoptosis, and that the survival of thyroid carcinoma cells, but not normal thyroid cell lines, depends on the activity of the ETS1 and ETS2 proteins." (PMID 39941022, 2025). "The results of rescue studies suggested that has_circ_0008234 influences the malignancy of colon cancer by regulating ETS1 via miR-338-3p." (PMID 37046729, 2023). "Meanwhile, we discovered that PI3K/AKT/mTOR signaling is the downstream pathway of the has_circ_0008234/miR-338-3p/ETS1 axis, which improves the effect network of circRNAs in colon cancer." (PMID 37046729, 2023). "In a previous study, we found a decrease in the expression of syndecan-1 and opposite trend for Ets-1 throughout colon carcinoma progression." (PMID 32977498, 2020). "Next, we analyzed the impact of ETS1 loss on cell viability and YK-4-279 sensitivity in the RKO colon cancer model." (PMID 33143299, 2020). "A recent paper has identified that the increased expression of INPP4B is due to transcriptional upregulation mediated by the transcription factor Ets-1 in colon cancer cells." (PMID 29343273, 2018). "A recent study demonstrated that the increase in INPP4B is due to Ets-1-mediated transcriptional upregulation in colon cancer cells." (PMID 29343273, 2018). "Ets-1 and MMPs co-expressed in colon cancer and other malignant tumor, and its expression degree would be increased with tumor invasion and metastasis extent accordingly, but its expression was very low in benign and non-invasive tumor." (PMID 25264483, 2014). "On the other hand, in colon cancer cells, the p42 form of the Ets-1 protein was shown to rescue Fas-induced apoptosis." (PMID 15365563, 2004). "In conclusion, hsa_circ_0008234 increases colon cancer proliferation, infiltration, and migration via the miR-338-3p/ETS1/PI3K/AKT axis; therefore, it could serve as a target and a focus for colon cancer therapy." (PMID 37046729, 2023). "We successfully overexpressed ETS1 in treated colon cancer cells." (PMID 37046729, 2023). "Along with the PI3K/AKT/mTOR signaling pathway, the hsa_circ_0008234/miR-338-3p/ETS1 axis may influence the activity of colon cancer malignancy." (PMID 37046729, 2023). "Previous research confirms that ETS1 overexpression can up-regulate the expression of matrix metalloproteinases to enhance the cancer cell migration and invasion in pancreatic, prostate, ovarian and colon cancers." (PMID 34889689, 2021). "Furthermore, the transcription factor p-ERK was investigated via an activation profiling array, which showed that only the activity of the transcription factor Ets1 was significantly inhibited in colon cancer cells treated with NCTD." (PMID 26846153, 2016). "Moreover, we found that hsa_circ_0008234 could promote proliferation, invasion, and migration abilities of colon cancers, which was partly dependent on the competitive endogenous RNA mechanism (miR-338-3p/ETS1 axis)." (PMID 37046729, 2023). "In the present study, we found combination of αvβ6 and Ets-1 could favor colon cancer prognosis." (PMID 25264483, 2014). "Hsa-mir-377 targets ETS1 to inhibit human clear cell renal cell carcinoma 38, targets E2F3 to inhibit non-small cell lung cancer 39, and targets BRD4 to inhibit colon cancer." (PMID 36741263, 2023). "Moreover, relatively high co-expression scores were also observed for RUNX2/ETS1, RUNX2/FOXO3, HNF1B/HNF4A, and HNF1B/FOXA3, suggesting that the DETFs associated with DARs might work together and be responsible for 5-FU resistance in colon cancer cells." (PMID 35252200, 2022). "In colon cancer, ETS1 expression is directly related to the malignancy, with no expression in normal tissues and the highest expression in carcinomas with lymph node metastasis." (PMID 39941022, 2025).
colon carcinoma (continued). "TGF-β-dependent signaling activates PTHLH expression by increasing transcription from the P3 promoter through a synergistic interaction of the transcription factors Smad3 and Ets1, and p38 MAPK-dependent signaling controls PTHLH expression in metastatic colon cancer cells." (PMID 31487323, 2019). "In the pathogenesis of metastatic CRC, abundant miR-200c could be detected in liver metastasis tissues, and overexpression of miR-200c in colon cancer cell lines led to a reduced expression of its target genes ZEB1, ETS1 and FLT1, and EMT markers (E-cadherin and vimentin)." (PMID 26064956, 2015).
autoimmune disease (18 papers, 2013 to 2025). A disorder resulting from loss of function or tissue destruction of an organ or multiple organs, arising from humoral or cellular immune responses of the individual to their own tissue constituents. "Numerous autoimmune disease-associated SNPs map near the human ETS1 gene and decreased Ets1 expression has been found in immune cells from autoimmune disease patients." (PMID 39149372, 2024). "In mice, loss of Ets1 leads to autoimmune disease with inappropriate activation of B cells, including autoreactive B cells, and their differentiation into plasma cells that secrete antibodies." (PMID 39149372, 2024). "Naïve CD4 + T cells isolated from Ets1 KO mice differentiate more readily to Th17 cells that secrete IL-17, a cytokine implicated in autoimmune disease pathogenesis." (PMID 37691956, 2023). "Several studies have revealed the effects of genetic variants that decrease ETS1 expression in autoimmune diseases." (PMID 31275358, 2019). "Over time, evidence has accumulated that Ets1 is a key regulator of B cell differentiation and that reduced levels of Ets1 are associated with the development of autoimmune diseases." (PMID 28439269, 2017). "Loss of Ets1 leads to premature B cell differentiation into antibody-secreting cells (ASCs), secretion of autoantibodies, and development of autoimmune disease." (PMID 28439269, 2017). "Examining the list of 263 genes, we identified numerous putative Ets1 target genes where SNPs have been associated with autoimmune disease susceptibility." (PMID 28439269, 2017). "In keeping with a role for Ets1 in establishing B cell tolerance, Ets1−/− mice develop an autoimmune phenotype and single-nucleotide polymorphisms (SNPs) in the human ETS1 gene have been highly implicated in a variety of autoimmune diseases." (PMID 28439269, 2017). "In this study, we show that Ets1 binds to and is required for normal expression of ~260 genes in mature B cells, including a subset of genes highly linked to immune responses and autoimmune disease susceptibility." (PMID 28439269, 2017). "In agreement with these autoimmune diseases, we observed that ETS-1 was also a susceptibility gene for RA at least in southern Han Chinese." (PMID 26241881, 2015). "Therefore, the ETS-1 gene polymorphism seems to play a crucial role in the mutual susceptibility for autoimmune diseases." (PMID 31873148, 2019). "List of potential Ets1 target genes associated with autoimmune disease." (PMID 28439269, 2017). "Interestingly, a cohort of genes associated with autoimmune disease susceptibility is among those that are regulated by Ets1." (PMID 28439269, 2017). "Because of clinical and immunological overlap of AS and other autoimmune diseases, ETS1 may be associated with AS as well." (PMID 24708692, 2014). "Moreover, the association of autoimmune diseases and SNPs in ETS1 gene is inconsistent in the epidemiologic literature, besides we only measured the rs4937333 SNP that might be associated with SLE." (PMID 31275358, 2019). "Ets1 mRNA levels are reduced in PBMCs isolated from patients with a variety of different autoimmune diseases." (PMID 39149372, 2024). "Loss of Ets1 in mice leads to excessive immune cell activation and development of an autoimmune syndrome and reduced Ets1 expression has been observed in human PBMCs in the context of autoimmune diseases." (PMID 39149372, 2024). "Given that aberrant expression of the Ets1 gene is found in autoimmune diseases, it is important to understand the regulatory mechanisms controlling its expression pattern." (PMID 39149372, 2024). "Together, these alterations in T-cell differentiation contribute to the progression of autoimmune disease in Ets1 KO mice, as evidenced by knockout of Ets1 specifically in T cells, which results in autoimmune disease." (PMID 37691956, 2023). "Mice that lack Ets1 (Ets1 KO) develop spontaneous autoimmune disease with high levels of autoantibodies." (PMID 37691956, 2023).
autoimmune disease (continued). "To test the role of IL-17 in promoting autoimmune disease in Ets1 KO mice, we crossed Ets1 KO mice to IL-17 receptor A subunit (IL17RA) KO mice to generate double knockout (DKO) mice." (PMID 37691956, 2023). "A number of studies have also shown low levels of Ets1 mRNA in PBMCs of patients with autoimmune disease." (PMID 31356162, 2019). "Genetic variants in ETS1, including rs1128334, rs4937333, and rs6590330, are associated with SLE and other autoimmune diseases in the Asian population, but these associations are less well replicated in the Asian population than in European populations." (PMID 31275358, 2019). "Given that normal expression of Ets1 is required to prevent autoimmune disease, it is interesting that a number of these Ets1 target genes are genes identified as susceptibility alleles of autoimmune diseases." (PMID 28439269, 2017). "In previous reports, some SNPs of ETS-1 were found to be significantly with many autoimmune diseases such as SLE, pediatric uveitis and celiac disease." (PMID 26241881, 2015). "ETS1 is a negative regulator of the Th17 differentiation gene and plays a central role in the pathogenesis of autoimmune diseases." (PMID 24708692, 2014). "The transcription factor Ets-1, originally discovered as an oncogene (v-ets) within the genome of the avian leukemia virus, shows a dual nature in autoimmune diseases." (PMID 24658012, 2014). "Animal experiments showed that autoimmune disease developed in ETS1-knockout mice, as investigated by the production of high titers of autoantibodies, and immune cell infiltration into organs accounted for aberrations in lymphocyte differentiation." (PMID 24708692, 2014). "Increasing evidence indicates that ETS-1 could contribute to the pathogenesis of autoimmune disease." (PMID 26241881, 2015). "What’s more, animal experiments showed that autoimmune disease developed in ETS-1 knockout mice, as investigated by the production of high titers of autoantibodies, and immune cell infiltration into organs accounted for aberrations in lymphocyte differentiation." (PMID 26241881, 2015). "This study might provide further evidence to improve our understanding of the exact function of ETS1 in the pathogenesis of autoimmune diseases." (PMID 24708692, 2014). "Additional Ets1 target genes include ones important for immune function such as Il5ra, Tlr1, Traf4, and Ltk, but that not yet been implicated as susceptibility loci for autoimmune disease." (PMID 28439269, 2017). "These traits are clinically related and colocalized at 13 loci, including sites near genes that regulate eosinophil biology (ETS1 and ID2) and autoimmune disease (KIAA1109 and TAGAP)." (PMID 32600345, 2020). "ETS-1, one of the most important transcription factors among the ETS families, regulates the proliferation, senescence and death of multitudinous immune cells and plays a multifunctional role in autoimmune diseases." (PMID 31873148, 2019).
bladder cancer (17 papers, 2014 to 2025). "All these data indicated GATA4 and ETS1 played essential roles in the drug resistance of MLL mutated bladder cancer cells." (PMID 26625313, 2016). "Moreover, GATA4 and ETS1 played an indispensable role in the drug-resistance of bladder cancer cells with MLL mutation." (PMID 26625313, 2016). "Additionally, the promoter of telomerase reverse transcriptase (TERT) gene frequently mutated in bladder carcinoma in which ETS1 bond to the altered promoter and promoted bladder carcinoma migration and progression." (PMID 26625313, 2016). "Thus, MLL mutation, GATA4 and ETS1 may be used as a the biomarkers for diagnosis and targets for treatment of bladder cancer recrudescence." (PMID 26625313, 2016). "We also demonstrated that the transcription factor ETS1 promotes PLA2G7 expression in bladder cancer." (PMID 40169540, 2025). "Collectively, these findings indicate that ETS1 positively regulates PLA2G7 expression in bladder cancer, thereby contributing to immune evasion." (PMID 40169540, 2025). "Transcription factor v-ets avian erythroblastosis virus E26 oncogene homolog 1 (ETS-1), a transcription factor that is highly expressed in bladder cancer cells, was targeted through synthetic biology methods involving the “simplify-test-concatenate” approach." (PMID 40747118, 2025). "To investigate the functional role of ETS1 in regulating PLA2G7 expression, we established bladder cancer cell lines with stable ETS1 knockdown." (PMID 40169540, 2025). "The luciferase test results suggest that the CRISPReader can significantly activate the expression of luciferase in T24, 5637, RT4 bladder cancer cell lines that highly express Ets-1, but cannot express luciferase in normal urothelial cells SV-HUC-1." (PMID 34124154, 2021). "MDR1 expression showed a quantitative linear correlation with Ets-1 expression at the transcriptional level in human bladder cancer patients according to the analysis using cBioPortal for cancer genomics." (PMID 32131547, 2020). "Although correlation exists between MDR1 and Ets-1 expression in bladder cancer patients, active Ets-1, Thr38 phosphorylated form (pThr38), was critical to induce MDR1 expression." (PMID 32131547, 2020). "In our study, we found that the expression level of ETS-1 was significantly up-regulated in bladder cancer tissues compared with matched normal tissues." (PMID 27036016, 2016). "We demonstrated that ETS-1 was up-regulated in human bladder cancer tissue compared to paired normal bladder tissue." (PMID 27036016, 2016). "Silencing ETS-1 observably suppressed the activity of artificial hTERT promoter in bladder cancer cell." (PMID 26743236, 2016). "The increased modification of H3K4me3 and expression of GATA4 and ETS1 would be the promising targets for the diagnosis and therapy of relapsed bladder cancer." (PMID 26625313, 2016). "In order to evaluate the role of ETS-1 in regulating human bladder cancer migration, bladder cancer 5637, T24 and UMUC-3 cells were treated with ETS-1 shRNA or the over-expression vector and analyzed by the cell migration assay afterwards." (PMID 27036016, 2016). "In this study, we aimed to investigate the relationship between the transcription factor ETS-1 and malignant phenotypes of bladder cancer." (PMID 27036016, 2016). "After that, we assessed the relationship between ETS-1 expression level and clinical-pathologic characteristics in 42 patients with bladder cancer." (PMID 27036016, 2016). "In conclusion, the results of this research demonstrate that ETS-1 is highly expressed in the bladder cancer compared to matched normal bladder tissue, and promotes bladder cancer cell migration and invasion." (PMID 27036016, 2016). "From our unpublished data, the expression levels of ETS-1 were significantly up-regulated in bladder cancer tissues compared with matched normal tissues." (PMID 26743236, 2016). "Silencing ETS-1 observably inhibited the activity of artificial hTERT promoter in bladder cancer cell." (PMID 26743236, 2016).